NGF (nerve growth factor)
Diseases named in the same sentence as NGF in open-access papers (continued):
Sharing a sentence is not in itself a finding about the gene and the disease.
hepatocellular carcinoma (5 papers, 2022 to 2025). A malignant tumor that arises from hepatocytes. "Moreover, NGF and its associated receptor are significant in influencing the pathophysiology of the intrahepatic biliary epithelium during liver tissue remodeling in cirrhosis and the progression of hepatocellular carcinoma." (PMID 38673940, 2024). "In the tumor tissues of patients with hepatocellular carcinoma, it was found that T cells invading the microenvironment bound to the largest part of the NGF secreted by cancer cells." (PMID 38791953, 2024). "In general, NGF upregulation after nerve injury is a sign of nerve regeneration, even though this compensatory reaction is sometimes deleterious (e.g., the role of NGF as a biomarker indicating hepatocellular carcinoma development after anti-hepatitis C treatment)." (PMID 40783715, 2025). "In the 1990s, researchers reported the use of ITs of TCS with Hepama-1 (human hepatoma), CMU15A (Lung cancer antigen), anti-p75-anti-mouse IgG (p75: nerve growth factor), Ng76 (Melanoma), and EGF (hepatocellular carcinoma)." (PMID 35324675, 2022).
incontinence (5 papers, 2013 to 2025). "We found significant differences in NGF and NT-3 that could predict diagnostic incontinence types." (PMID 40134822, 2025). "The result showed that serum NGF and NT-3 levels were significantly low in both incontinence subtypes compared to the control group (p < 0.05)." (PMID 40134822, 2025). "One of the most promising applications of NGF-related treatments in SCI therapy is the management of urinary incontinence." (PMID 40153582, 2024). "While it may promote spinal cord repair and the survival of both spinal and DRG neurons, NGF-related mechanisms are also associated with significant clinical symptoms of SCI, such as neuropathic pain and urinary incontinence." (PMID 40153582, 2024). "Higher serum NGF levels in OAB-wet, but not OAB-dry, than in the controls could be explained by more neuromuscular factors in OAB-wet bladders, which might be responsible for the symptoms of urinary incontinence." (PMID 24098552, 2013).
liver cancer (5 papers, 2021 to 2025). An epithelial or non-epithelial malignant neoplasm that arises from the liver. "Several reports have suggested that NGF plays an integral part in the progression of several types of malignancies such as ovarian, prostate and liver cancers." (PMID 34283074, 2021). "For example, NGF plays a significant role in liver cancer progression and metastasis, exerting wide influences on liver cancer cell polarity and motility by regulating signaling pathways involved in cell movement, cytoskeletal organization, and cellular polarity." (PMID 38392180, 2024).
liver diseases (5 papers, 2014 to 2020). "During liver diseases, hepatocytes produce NGF as well as its precursor form, pro-NGF; binding of NGF to p75NTR induces apoptosis in HSCs." (PMID 31940814, 2020). "This study evaluated the relative mRNA expression levels of nerve growth factor (NGF) and the p75 neurothrophin receptor (p75NTR) in different histological stages of human liver disease." (PMID 25816145, 2015). "Additionally, the NGF pathway has been previously reported to be induced by inflammatory cytokines in experimental models of liver disease." (PMID 31150430, 2019). "Therefore, to elucidate which receptor is responsible for the NGF-exhibited hepatoprotection is imperative to further understand the role of NGF in various liver diseases." (PMID 25397406, 2014).
lung disease (5 papers, 2014 to 2023). "Under different microenvironments, NGF participates in the occurrence and development of lung diseases by changing protein expression levels and mediating cell function." (PMID 34502019, 2021). "In the following sections, the relationship between NGF and these lung diseases is described in detail." (PMID 34502019, 2021). "Studies have found that NGF participates in the occurrence and development of lung diseases and may serve as a therapeutic target." (PMID 34502019, 2021). "Therefore, these factors seem to be helpful in exploration of the mechanisms by which NGF affects the occurrence and development of lung disease." (PMID 34502019, 2021). "In recent decades, interest in the role of NGF in lung diseases has increased." (PMID 34502019, 2021). "In this review, we summarize the functions of NGF and highlight its effects on lung diseases." (PMID 34502019, 2021). "In view of the substantial evidence linking NGF to pulmonary diseases, as well NGF's ability to alter ion transport in PC12 and the MTAL cells, we hypothesized that NGF is involved in the regulation of ion transport in airway epithelial cells." (PMID 25347857, 2014). "The significant Ago2-IP enrichment of targets of these miRNAs related to the TGF-β and/or Wnt pathways (NGF, DLD, HHEX) in TGF-β1-stimulated fibroblasts suggest a role for these miRNAs in lung diseases by affecting lung fibroblast function." (PMID 28910321, 2017).
lymph node metastasis (5 papers, 2006 to 2023). "These are compatible with our clinical findings from more than 100 cases of immunohistochemistry that overexpression of NGF is associated with lymph node metastasis and associated with poorer clinical outcome." (PMID 16832412, 2006). "Immunohistochemical study of 109 OESCC specimens revealed that NGF overexpression, found in 63 out of 109 patients (57.8%), was associated with lymph node metastasis, distant metastasis, higher TNM stage, poorer tumour differentiation, and poorer survival." (PMID 16832412, 2006). "The expression of NGF was markedly higher in cases involving elderly patients, advanced-stage disease, and lymph node metastasis." (PMID 32508884, 2020). "A high level of expression of neurotrophic factors including BDNF and NGF correlates closely and positively with a high FIGO stage, lymph node metastasis, the growth of neurons, and poor long-term outcomes in OC." (PMID 37799274, 2023).
medulloblastoma (5 papers, 2015 to 2025). A malignant, invasive embryonal neoplasm arising from the cerebellum. "In addition, NGF administration blocked medulloblastoma proliferation and induced overexpression of p73 in ependymoblastoma clones." (PMID 39056738, 2024). "Subsequent studies in rodent L6 myoblasts and human medulloblastoma D283MED-TrkA (MB-TrkA) cells revealed that STK25 undergoes autophosphorylation in response to TNF-α and nerve growth factor (NGF), respectively." (PMID 40639948, 2025). "As in the preceding examples of cell death associated with abnormal macropinocytosis, siRNA-mediated knockdown of autophagy proteins (e.g., Beclin-1, Atg5, LC3) did not prevent the accumulation of vacuoles or cell death in NGF-stimulated medulloblastoma cells." (PMID 25762935, 2015).
meningitis (5 papers, 2017 to 2024). A disorder characterized by acute inflammation of the meninges of the brain and/or spinal cord. "NGF expression decreased in the meningitis/tamoxifen group when compared to the control/saline and meningitis/saline (P < 0.05) groups." (PMID 29200666, 2017). "In NGF expression in the hippocampus, there were effects for meningitis (F = 17.07; P < 0.001) for treatments (F = 13.15; P < 0.001), as well as interaction (F = 8.11; P = 0.002)." (PMID 29200666, 2017). "Supported by these hypotheses and evidence, it has been recently described the outcomes of human-recombinant nerve growth factor (hr-NGF) treatment in an infant six months after a group B Streptococcus (GBS) meningitis." (PMID 39056738, 2024). "More significantly, all vital biotargets of calycosin-anti-meningitis were eventually identified, including EGFR, TNF, EGF, ATM, ESR1, CASP8, NGF." (PMID 33031061, 2020).
myocardial ischemia (5 papers, 2009 to 2025). A disorder of cardiac function caused by insufficient blood flow to the muscle tissue of the heart. "Since mature NGF had been observed to mediate Akt/mTOR inhibition of autophagic flow activation in myocardial ischemia-reperfusion, the function of mature NGF and proNGF after CIR may potentially correlate with this kind of signaling." (PMID 35391929, 2022). "NGF is also important for sensory innervation, and NGF downregulation may result in silent myocardial ischemia and SCD in diabetic patients." (PMID 21037846, 2009). "In addition, antithrombin-98-5p has been shown to alleviate microvascular dysfunction and enhance the expression of NGF and TRPV1 in a rat myocardial ischemia/reperfusion model." (PMID 40217309, 2025). "Cardiac sensory function, measured by myocardial ischemia-induced c-Fos expression in dorsal root ganglia, was also downregulated by DM in the WT mice, but not in the NGF-transgenic mice." (PMID 21037846, 2009).
preeclampsia (5 papers, 2015 to 2023). Preeclampsia is a hypertensive disorder of pregnancy that is characterized by new-onset hypertension with proteinuria presenting after 20 weeks of gestation, and depending on mild or severe forms may initially present with severe headache, visual disturbances, and hyperreflexia. "The NGF guideline suggests similar cardiovascular follow-up by a general practitioner in line with what the Society also suggests after a pregnancy complicated by preeclampsia." (PMID 35796791, 2022). "Because inadequate trophoblast invasion and endothelial dysfunction are important features in the development of preeclampsia, and because SSRI-treated women had increased levels of ROCK2 in trophoblasts it may be speculated that NGF signaling also plays a role in preeclampsia." (PMID 25611484, 2015). "This feature would explain the low cord blood NGF levels in preterm SGA newborns and in those delivered after pregnancies complicated with preeclampsia, gestational diabetes, or other disorders, where the timing of NGF secretion, release, and/or transport may be significantly affected." (PMID 30675161, 2018).
pressure ulcers (5 papers, 2014 to 2025). "A randomized clinical trial has also indicated that topical application of NGF could accelerate the wound-healing process in 18 selected patients with pressure ulcers of the foot." (PMID 25006578, 2014). "Topical application of NGF also promotes skin ulcer healing in patients with pressure ulcers." (PMID 25006578, 2014). "In addition, clinical studies on pressure ulcers found that, after the topical NGF treatment, the area of pressure ulcers on the elbow was reduced to the control group, and the rate of recovery is irrelevant to the severity of the ulcer, the patient’s age or the surgical site." (PMID 38049878, 2023). "Studies in humans revealed that topical administration of NGF was a promising approach for the treatment of cutaneous pressure ulcers, and the topical application of NGF may also represent a new useful tool for the management of difficult diabetic ulcers or severe pressure ulcers." (PMID 32283613, 2020).
pulmonary hypertension (5 papers, 2016 to 2023). Increased pressure within the pulmonary circulation due to lung or heart disorder. "Monocrotaline-induced pulmonary hypertension is associated with increased NGF protein in lung tissue." (PMID 33082140, 2020). "Expression of the nerve growth factor NGF is increased in pulmonary hypertension (PH)." (PMID 36139373, 2022).
retinoblastoma (5 papers, 2021 to 2025). A malignant tumor that originates in the nuclear layer of the retina. "Since TRPs like TRPV1 and TRPM8, as well as NGF receptors (TrkA), are (over)expressed in tumors such as uveal melanoma (UM) or retinoblastoma, we tested NGF on calcium regulation in human UM cells for comparison purposes." (PMID 40422222, 2025). "According to currently available data, an increased signal for activators of the MAP-Kinase pathway, such as NGF, epidermal growth factor (EGF), and platelet-derived growth factor (PDGF), was found in pediatric retinoblastoma cell samples." (PMID 39056738, 2024).
thyroid cancer (5 papers, 2016 to 2025). "Using the ebi-a-GCST90018929 dataset for MR analysis, the inverse variance weighted (IVW) analysis results indicated that IL-1 receptor antagonist (IL-1RA) and beta-nerve growth factor (B-NGF) were risk factors for thyroid cancer, whereas M-CSF acted as a protective factor." (PMID 40892159, 2025). "The precursor for nerve growth factor (proNGF) has recently been shown to be overexpressed in thyroid cancer compared to benign thyroid tissues, suggesting utility as a discriminator in diagnostic testing." (PMID 31775768, 2019). "Although NGF has been described in thyroid cancer, it has not been associated with any clinicopathological features." (PMID 27074571, 2016). "In terms of gene expression, NGF mRNA abundance has not been reported to be linked to a particular clinicopathological parameter in thyroid cancer." (PMID 27074571, 2016). "The precursor for Nerve Growth Factor (proNGF) is overexpressed in thyroid cancer, but its potential role as a clinical biomarker has not been reported." (PMID 31775768, 2019). "The precursor for nerve growth factor (proNGF) is increased in primary thyroid cancers, but its expression or significance in metastases is not known." (PMID 31775361, 2019).
age-related macular degeneration (4 papers, 2020 to 2022). Age-related loss of vision in the central portion of the retina (macula), secondary to retinal degeneration. "Age-related macular degeneration (AMD) is a retinal disease which represents the major cause of blindness in developed countries and shares several clinical and pathological features with AD, including alterations in NGF transduction pathways." (PMID 34566573, 2021).
atrial fibrillation (4 papers, 2018 to 2023). A disorder characterized by an electrocardiographic finding of a supraventricular arrhythmia characterized by the replacement of consistent P waves by rapid oscillations or fibrillatory waves that vary in size, shape and timing and are accompanied by an irregular ventricular response. "This is corroborated by studies that identify increased NTRK1/TRKA levels associated with atrial fibrillation, and is further supported by data that revealed concomitant autocrine and paracrine regulation of NTRK1/TRKA expression by upstream NGF." (PMID 29848314, 2018). "Can the spinal cord stimulation (SCS) regulate the autonomic nerves through the endothelin-1 (ET-1) and nerve growth factor (NGF)/p75NTR pathways and thus inhibit the occurrence of atrial fibrillation (AF)?" (PMID 37808162, 2023).
benign prostatic hyperplasia (4 papers, 2014 to 2023). A non-cancerous nodular enlargement of the prostate gland. "NGF and its receptors have been identified in normal prostatic tissue, benign prostatic hyperplasia and prostatic cancer, suggesting a potential role in the cell biology of these tissues." (PMID 25187831, 2014). "Prostate tissue derived from normal, benign prostatic hyperplasia and adenocarcinoma specimens has indicated that NGF immunoreactive protein is localized in the stromal compartment." (PMID 25187831, 2014). "Analysis of mRNA and DNA has shown that prostate stromal smooth muscle cells express NGF, and immunohistochemistry studies have shown that NGF is localized not only in the stromal compartment of normal and carcinoma samples, but also in benign prostatic hyperplasia and epithelial PC cells." (PMID 36941697, 2023). "Regarding NGF and PDGF, studies have shown their involvement in the development of prostatic hyperplasia, and revealed that NGF and PDGF production in the prostate is one of the possible etiologies of BPH." (PMID 36769190, 2023).
brain tumor (4 papers, 2018 to 2025). "Podoplanin, a cell surface glycoprotein, is highly expressed under pathological conditions, including brain tumours, and interacts with nerve growth factor (NGF), a well-established neurotrophin essential for the maintenance and plasticity of hippocampus-dependent memory circuits." (PMID 40806177, 2025).
bronchiolitis (4 papers, 2009 to 2025). Inflammation of the bronchioles characterized by swelling of the bronchioles and mucus accumulation. "Elevated neutrophil activation, IL-8, and NGF in severe bronchiolitis; limited predictive biomarkers identified." (PMID 41583233, 2025).
cardiomyopathies (4 papers, 2013 to 2025). "Moreover, as a potent booster of cardioprotective NGF in vivo, PDNF may offer a novel therapeutic opportunity against cardiomyopathies." (PMID 23437390, 2013).
cholestasis (4 papers, 2014 to 2023). Impairment of the bile flow caused by obstruction within the liver, or outside the liver in the bile duct system. "Beta nerve growth factor (b-NGF) is part of the biliary hyperplasia regulation during cholestasis and enhanced expression had been measured in primary sclerosing cholangitis." (PMID 34062967, 2021). "For instance, NGF, also reportedly produced by cholangiocytes, was demonstrated to promote cholangiocyte proliferation, which is one of the hallmarks of cholestasis." (PMID 25397406, 2014). "Since NGF has been previously reported to be up-regulated by inflammatory cytokines in diseased bladder, aorta, heart, and livers, we next to determine whether anti-inflammatory treatment could ameliorate the cholestasis-associated NGF up-regulation in injured livers." (PMID 25397406, 2014). "Additionally, nerve growth factor (NGF) was found to be secreted by cholangiocytes in an experimental mouse cholestasis model." (PMID 37261338, 2023). "Moreover, we also demonstrated that cholestasis-related inflammatory signaling such as TGF-β1 was able to induce NGF expression in cultured hepatocytes." (PMID 25397406, 2014). "Although NGF has been reported to be up-regulated during experimental cholestatic injury, its role in hepatocytes following oxidative injury and its mechanism of regulation during cholestasis remain unclear." (PMID 25397406, 2014). "Although the present study demonstrated the molecular mechanisms of NGF regulation and its protective effects in hepatocytes, more studies are needed to determine whether the pathological changes of cholestasis could be ameliorated through manipulation of NGF receptor signal axis in vivo." (PMID 25397406, 2014).